IFIT2 (interferon induced protein with tetratricopeptide repeats 2)
Diseases named in the same sentence as IFIT2 in open-access papers (continued):
Sharing a sentence is not in itself a finding about the gene and the disease.
tumor (47 papers, 2014 to 2026). "Overall, more evidence supports the notion that IFIT2 acts as a tumor suppressor and its expression associates with favorable clinical outcomes." (PMID 40564154, 2025). "In OSCC, commonly found higher expression of IFIT2 protein in cancer tissues is associated with better patient survival, increased tumor differentiation and lower nodal stage of disease." (PMID 40564154, 2025). "Intriguingly, IFIT1, IFIT3 and IFIT5 proteins play significant roles in malignant progression, whereas numerous reports have shown that decreased IFIT2 expression is associated with tumor progression and poor survival of patients with different cancers." (PMID 33256074, 2020). "In particular, increased IFIT1 and IFIT3 expression has been correlated with improved therapeutic response to chemotherapeutics and immunostimulating agents and increased IFIT2 expression in the tumour tissues of patients was associated with improved patient survival." (PMID 36579897, 2023). "IFIT2 knockdown significantly increased IL-6 mRNA and secretion levels in OSCC cells, indicating IFIT2's potential regulatory role in inflammation within the tumor microenvironment." (PMID 41619016, 2026). "We observed significant upregulation of the transcriptional levels of Ifnb1, Ifit1, Ifit2, Ifit3, Irf7, and Mx1 in irradiated 4T1 tumor tissues and irradiated CT26, H22, and GL261 carcinoma cells." (PMID 40470716, 2025). "The TPR of IFIT2 induces apoptosis in tumor cells through the mitochondrial pathway, thereby exerting an antitumor effect." (PMID 40909948, 2025). "Although the clinical relevance of IFIT2 in other gastrointestinal tract cancers has yet to be understood, studies from these cancer types suggest that this protein behaves as a tumor suppressor." (PMID 40564154, 2025). "The results showed that the expressions of YTHDC2, OAS1, and IFIT2 were all reduced in tumor tissues, whereas the expression of RAB5A was increased in tumor tissues." (PMID 39303913, 2024). "Considering the important role of immune checkpoint molecules in tumor immune response, the relationships between IFIT2/3/5 mRNA levels and immune checkpoints expression in AML were also explored through TCGA database." (PMID 37980495, 2023). "Our previous study showed increased TNF-α expression in IFIT2-depleted metastatic and xenograft-derived sublines, and its inhibition resulted in decreased tumor growth, abolished angiogenic activity, and inhibited metastasis." (PMID 36979874, 2023). "Elevated levels of IFIT1, IFIT3 and IFIT5 have been shown to play significant roles in cancer progression, while the decreased expression of IFIT2 has been reported to enhance invasion, tumor progression, and drug resistance in various cancer types." (PMID 36979874, 2023). "When we used TCGA pancancer data to analyze the expression levels of the model’s key genes, METTL3 and IFIT2 were observed to have extensively different expression levels in regular and tumor tissues." (PMID 36386128, 2022). "The data from our and other groups have confirmed that IFIT2 can serve as an important tumor suppressor gene, and decreased expression of IFIT2 significantly associated with cancer progression and poor prognosis of the patients." (PMID 35107757, 2022). "IFIT2 was significantly inversely correlated with tumor purity (p = 9.77e-05), B cells (p = 9.68e-03), CD4+ T cells (p = 7.10e-04), macrophages (p = 2.20e-03) and neutrophils (p = 6.34e-03)." (PMID 36386128, 2022). "IFIT2 has been reported to be involved in the regulation of cell cycle, apoptosis, tumor colonization, and viral replication." (PMID 35386334, 2022). "We further measured the protein level of IFIT2 in the tumor tissues of 96 ICC patients by IHC staining." (PMID 35094011, 2022). "In tumor-infiltrate Tregs, we found that IFIT2, CCL3, RBPJ, etc. were upregulated in GC tissues compared to adjacent normal tissues while IGJ, XCL1, XCL2, etc. were downregulated." (PMID 32039830, 2020).
tumor (continued). "It has been confirmed that IFIT2 is an important tumor suppressor to tumor growth, invasion, and metastasis." (PMID 29254221, 2017). "Consistent with previous results, the expression of IFIT2 was downregulated in tumor compared to para-tumor (p<0.01)." (PMID 29254221, 2017). "Common up-regulated genes are related to transcription regulation (HMBOX1, LINC00340, NEXN-AS1), immune response (CD86, IL6, IFIT2) and the last two are potential tumor suppressors (LRRC2 and SPINK6)." (PMID 28035074, 2017). "Consistently with vitro, IFIT2 knockdown resulted in increased tumor growth (p<0.01) and decreased apoptosis (p<0.01) in tumors from nude mice transplanted with LM3-LINC00364-ShIFIT2 cells compared to control group." (PMID 29254221, 2017). "IFIT2 is well known as an important inducer of apoptosis and therefore serves as an important tumor suppressor." (PMID 29254221, 2017). "Of note, overexpression of TGFBI and interferon-induced proteins IFIT2, IFIH1 and IFI44L in the residual tumor were also associated with reduced RFS." (PMID 26021444, 2015). "As miRNAs function mainly through the inhibition of multiple target genes and study report that miR-645 inhibits apoptosis by targeting tumor suppressor IFIT2." (PMID 26388702, 2015). "Namely, tumor size greater than or equal to 5 cm group showed significant down-regulated IFIT2 expression compared with tumor size less than 5 cm group." (PMID 25174799, 2014). "Among them, IFIT2, a tumor suppressor, was found to have putative miR-645 binding sites within its 3′UTR." (PMID 25174799, 2014). "IFIT2 has been reported to be a tumor suppressor via mediating cell apoptosis through activating caspase-3/7 activity." (PMID 25174799, 2014). "Interferon-induced protein with tetratricopeptide repeats 2 (IFIT2) has been identified as a tumor suppressor in OSCC, though its role in bone invasion remains unclear." (PMID 41619016, 2026). "These tumor suppressive effects of IFIT2 in CRC have been proposed to be regulated by a blockage of its degradation by inhibition of proteasome activity and subsequent aggregation of IFIT2 in the centrosome and suppression of the JAK1/STAT/IFIT2 network by the Ajuba scaffold protein." (PMID 40564154, 2025). "The IFN-γ/STAT1 pathway upregulates the expression of IFIT2, leading to the initiation of apoptosis by modulating the balance between anti- and pro-apoptotic factors, thereby regulating mitochondrial permeability and inducing the death of tumor cells." (PMID 40909948, 2025). "IFIT2 (interferon-induced proteins with tetratricopeptide 2) gene is a crucial interferon-stimulated gene family protein, which has been confirmed to play an important role in the anti-tumor process inhibiting the proliferation and migration of cancer cells." (PMID 37046696, 2023). "The in vivo tumor-initiating properties of cells are also hallmarks of CSCs; hence, we performed an in vivo tumorigenicity assay by subcutaneously transplanting the stable IFIT2 knockdown and sh-control cells into the flanks of the nude mice." (PMID 36979874, 2023). "IFIT2 has been reported as a tumor suppressor for several tumor types." (PMID 35094011, 2022). "IFIT2 may be crucial in controlling the inflammatory tumor environment during metastasis in OSCC, which results in cachexia." (PMID 36386128, 2022). "In particular, overexpression of IFIT2 promotes tumor cell death." (PMID 36386128, 2022). "IFIT2 has been recognized as an important tumor suppressor gene in our and other’s studies, and decreased IFIT2 expression significantly increased the cellular ability of invasion and migration, and lower level of IFIT2 expression in cancer tissues can predict the poor survival of the patients." (PMID 35107757, 2022). "Moreover, SEMA3A, PTPRH and IFIT2 were found to have significant effects on tumour inhibition and functioned as promising therapeutic agents for cancers." (PMID 33145887, 2021).
tumor (continued). "Strikingly, high IFIT2 expression in tumor tissues was correlated with better patient survival." (PMID 31921891, 2019). "Besides, the high expression of IFIT2 in OSCC tumor tissues negatively correlated with the nodal stage." (PMID 31921891, 2019). "The negative association of IFIT2 with tumor malignancy is likely due to its pro-apoptotic activity." (PMID 31921891, 2019). "In contrast, IFIT2 has been shown to have tumor suppressor function in many cancers." (PMID 31921891, 2019). "Particularly, IFIT2 overexpression in tumor cells promotes tumor cell death." (PMID 28878208, 2017). "Furthermore, it was indicated that the inhibition of Malat1 led to upregulation of the downstream tumor suppressor (e.g., interferon-induced protein with tetratricopeptide repeats 2 [IFIT2]), verifying the capacity of PS-LSNAs as therapeutics and biological tools." (PMID 38951806, 2024). "Finally, it has been suggested that IFIT proteins could be a novel therapeutic target for tumor therapy, so IFIT2 could become a possible target in NB too." (PMID 37046696, 2023). "For evaluating the role of PTEN expression on cGAS-STING activity and tumour immunogenicity, mRNA expression levels of interferon-stimulated genes, especially IFNB, IFIT2, IFI44, and IL6 were analysed." (PMID 38214828, 2024). "In the group of novel hub genes, low expression levels of UBE2L6, KIR2DL4, IFIT2, and CLEC4E were observed in tumor cells, while high expression levels of SRPX2 and EDN3 were found in SKCM." (PMID 34660598, 2021). "Interferon-induced protein with tetratricopeptide repeats 2 (IFIT2), one of the top 10 upregulated genes induced by ILA, is an anti-viral protein preventing tumor progression and regulating viral replication." (PMID 33850185, 2021). "In IFIT2-knockdown cells, the 5-FU and SAHA combination resulted in a significant 61–64% reduction in tumor volume, while 5-FU alone resulted in a 27–39% reduction, and SAHA alone resulted in a 12–41% reduction." (PMID 33256074, 2020). "In contrast, decreasing IFIT2 expression activated PKC pathway and promoted the progression of tumor malignancy." (PMID 31921891, 2019). "Although IFIT2 belongs to the same family, it executes tumor suppressor functions, whereas IFIT1 and IFIT3 have tumor-promoting properties in OSCC." (PMID 31921891, 2019). "We also demonstrate for the first time that HSP90 inhibition upregulates interferon response genes in the tumor, notably IFIT1, IFIT2 and IFIT3, both in vitro and in vivo." (PMID 28878208, 2017). "We now show that IFIT2 and other family members IFIT1 and IFIT3, when overexpressed in tumor cells, enhance T-cell killing of tumor cells." (PMID 28878208, 2017). "IFIT-silenced and control tumor cell lines were generated by simultaneously transducing tumor cells with IFIT1, IFIT2 and IFIT3 small hairpin RNAs (shRNA) or with scrambled shRNA, respectively." (PMID 28878208, 2017). "In particular, when the cell inoculation number was at least ten cells, there was no tumor growth in the sh-control group, but tumor formation was still observed in the IFIT2 knockdown cells." (PMID 36979874, 2023). "Six genes CCSER2, AGAP11, IFIT2, PAPSS2, PCGF5, and NUDT9P1 were observed to have potential NB tumor suppressor activity since their low expression was associated with poor survival even after correction for confounding by other prognostic factors (MYCN status, age at diagnosis, stage of disease)." (PMID 37046696, 2023). "It was found AGEJ tissues had a remarkable lower expression level of IFIT2 than the paired non-cancerous tissues, and IFIT2 expression was inversely correlated with the tumor size (P = 0.0304)." (PMID 25174799, 2014). "Highly expressed IFIT2 and NDRG1 could reduce tumor migration and metastasis." (PMID 35096568, 2021).
tumor (continued). "Likewise, mRNA levels of Ifit1 and Ifit2, two type I IFN-stimulated genes (ISGs), were also elevated in Ptgs2−/− tumors, indicative of enhanced type I interferon (IFN-α/β) signaling, which is central to immune-mediated tumor control." (PMID 26343581, 2015).
cancer (34 papers, 2015 to 2025). A tumor composed of atypical neoplastic, often pleomorphic cells that invade other tissues. "IFIT2 homodimers are known to enhance the apoptosis pathway, which has been implicated in its role in controlling certain types of cancers." (PMID 40497724, 2025). "For example, in colorectal cancer (CRC) where IFIT2 expression has been reported to be significantly lower in patients’ cancer relative to normal tissues, its exogenous expression led to decreased cell proliferation and increased apoptosis." (PMID 40564154, 2025). "Conversely, IFIT2 has been identified as a tumor suppressor gene and numerous studies have demonstrated that its knockdown significantly increases cancer cell proliferation in various tumors." (PMID 40463504, 2025). "Among them, IFIT2 stands out for its unique ability to inhibit cancer cell proliferation, making it a promising candidate for further research against M. tb." (PMID 40463504, 2025). "In another type of head and neck cancer (HNC), nasopharyngeal carcinoma, microarray data analysis indicated that the expression of IFIT2 is downregulated in chemoradiotherapy-resistant cancer cells compared to that of sensitive cells." (PMID 40564154, 2025). "Previous studies have already established the involvement of IFIT2 in apoptosis and attributed this to its ability to inhibit cancer cell proliferation." (PMID 40463504, 2025). "This suggests a potentially positive prognosis for patients with cancer undergoing TB treatment that targets IFIT2." (PMID 40463504, 2025). "Pro-apoptotic and antiproliferative properties of IFIT2 have been reported in a range of cancer types, such as SKCM, respiratory cancers, gastrointestinal cancers, cervical cancer cells, leukemia cell lines and osteosarcoma cells." (PMID 40564154, 2025). "A total of 404 co-correlated genes of IFIT2/3/5 were identified, and KEGG analysis indicated that these genes associated with several pathways, such as “Pathways in cancer”, “Necroptosis” and “Apoptosis”." (PMID 37980495, 2023). "Increased apoptosis from IFIT2 stimulation has been accomplished in cancer cell lines treated with proteasome inhibitors." (PMID 36851555, 2023). "On the contrary, increased IFIT2 expression inhibits cell proliferation and triggers apoptosis in various cancer types." (PMID 36979874, 2023). "IFIT2 has been confirmed to play an important role in suppressing proliferation and migration of cancer cells, and regulation of viral replication, showing anticancer effects and IFN-mediated antiviral effects." (PMID 35107757, 2022). "IFIT2, an important member of ISG family, is also known as ISG54, and it has been reported to play an important role in anti-viral and anti-cancer effects." (PMID 35107757, 2022). "Restricted cell cycle genes in interferon-inducible pathways include antiviral and anti-cancer activity (Ifit1 and Ifit2) and pro-inflammatory reactions recruiting immune cells to target cells (genes Stat1 and Unc5cl)." (PMID 34202278, 2021). "Overexpression of the IFIT2 protein was found to inhibit proliferation or promote apoptosis in a variety of cancer cell lines." (PMID 33256074, 2020). "Among these ISGs, IFIT2 is a well-established tumor suppressor, which was reported to enhance apoptosis, inhibit proliferation, migration, and invasion in numerous cancers." (PMID 29358655, 2018). "In addition, IFIT2 has been shown to serve as a favorable clinical indicator in several cancer types." (PMID 40564154, 2025). "Specifically, the IFIT2/Ifit2-mediated regulation of many processes involving microtubules, including apoptosis, proinflammatory signatures, phagocytosis, metabolism, and cancer cell migration, beckons further investigation into its interactions with microtubule proteins." (PMID 38140641, 2023).
cancer (continued). "Examining the relationship between IFIT2 depletion and CSCs may be helpful for proposing an approach to block cancer progression, recurrence, and metastasis, to overcome drug resistance, and to stratify patients based on optimal treatment regimens." (PMID 36979874, 2023). "Notably, HLA-I– cancer cells acquiring a mesenchymal status were associated with enhanced mRNA levels of the IFN-stimulated genes IFIT1, IFIT2, IFIT3, IFI6, IFI27, and CCL2." (PMID 35503263, 2022). "It is highly consistent with previous studies that IFIT2 is down-regulated in human cancers." (PMID 34660323, 2021). "IFIT2 has been demonstrated to perform important anti-cancer and anti-virus functions." (PMID 34660323, 2021). "Exploration of the role of IFIT2 in chemoresistance may provide valuable information to propose strategies to block cancer progression and metastasis and identify the correct regimen for treatment." (PMID 33256074, 2020). "In addition to its anti-viral activity, IFIT2 expression has been reported to inhibit cancer cell growth and migration." (PMID 30875792, 2019). "In this study, we discovered that IFIT1 and IFIT2 are negatively regulated by Wnt signaling in CRC cells and that suppressed expression of IFIT2 may confer pro-survival properties to cancer cells." (PMID 29245969, 2017). "For example, AKR1C2 may facilitate cancer cell autophagy and apoptosis, and IFIT2 inhibits cell motility and invasiveness by EMT." (PMID 28881746, 2017). "IFIT2 immunostaining could be found in the cytoplasm of cancer cells." (PMID 35107757, 2022). "We then plotted the expression profile of the top four upregulated ISGs (IFIT2, ISG15, IFIT1 and IFIT3) among various cancer types from the TCGA database." (PMID 38926796, 2024). "Although more work is required to accurately elucidate the impact of IFIT proteins in cancer, recent investigations reveal that IFIT1, IFIT3, and IFIT5 promote metastasis, while IFIT2 acts against neoplastic cells by promoting apoptosis." (PMID 36851555, 2023). "Among 33 types of human cancers, IFIT1, IFIT2, IFIT3, IFIT5 were abnormally expressed in 21, 23, 24 and 23 cancer types respectively." (PMID 37980495, 2023). "Moreover, IFIT2 depletion in metastatic OSCC cells induced muscle atrophy and cancer cachexia in mouse xenograft models by promoting IL6 (interleukin 6) production." (PMID 40564154, 2025). "While the function of IFIT2 in other cancers is still under investigation, current findings indicate that IFIT2 plays a negative role in neoplastic cells by reducing migration and promoting apoptosis." (PMID 36851555, 2023). "Mice that lack the IFIT2 gene succumb to several negative-strand RNA virus infections, and expression of IFIT2 has been reported to inhibit proliferation and migration of cancer cells as well as promote their apoptosis (24, 26, –, 30)." (PMID 29666281, 2018). "Since activation of Wnt signaling in cancer cells decreased both IFIT1 and IFIT2, co-repression of these genes may confer the pro-survival properties to the cancer cells by increasing resistance to apoptotic signals." (PMID 29245969, 2017). "While the absence of IFIT2 was shown to promote the activation of aPKC and induce EMT during OSCC, IFIT2’s function as a proapoptotic factor may also result in increased cancer survival when present in neoplastic cells." (PMID 36851555, 2023).
cardiac diseases (2 papers, 2021 to 2024). "It is significant evidence that that three signature genes (IFIT2, IFIT3 and IFI44L) are linked to heart disease and used as potential biomarker for ISCM." (PMID 34884921, 2021). "Previous studies have also reported the involvement of IFIT2 and IFITM2 in cardiac diseases." (PMID 38355637, 2024).